SYK (spleen associated tyrosine kinase)
Diseases named in the same sentence as SYK in open-access papers (continued):
Sharing a sentence is not in itself a finding about the gene and the disease.
tumor (continued). "There are two SYK isoforms in tumor cells, the full-length SYK (SYK-L) and the variable splice SYK transcript (SYK-S)." (PMID 36132125, 2022). "To test this possibility, we treated neutrophils with the SYK inhibitor R406 (10 μM) prior to their addition to the tumor cell culture." (PMID 35453656, 2022). "Increasing evidence suggests that SYK is essential for tumor cell proliferation, metabolism, and metastasis." (PMID 35435107, 2022). "SYK expression was significantly higher in tissues from 25 types of tumors and lower in two types of tumor tissues (p < 0.05)." (PMID 35910221, 2022). "To validate the expression pattern of SYK, we also collected 22 fresh normal and 175 tumor tissues from Xiangya Hospital, Central South University, and 37 paired tumor and peritumoral tissues." (PMID 35910221, 2022). "The abundance of SYK is negatively correlated with breast cancer progression and inhibits tumor growth and metastasis in xenografts." (PMID 35435107, 2022). "Both control and R406-treated neutrophils killed tumor cells to a similar extent, suggesting that SYK-dependent signaling is dispensable for this particular neutrophil function." (PMID 35453656, 2022). "SYK possesses controversial pro-tumor and anti-tumor properties in hematopoietic and other cell types." (PMID 35910221, 2022). "To further explore the differences in SYK expression between tumor and normal tissues, we obtained SYK expression data from 25 types of tumors and normal tissues from the TCGA database." (PMID 35910221, 2022). "Tumor growth and metastasis are developed and activated through the SYK signaling pathway as an intermediate." (PMID 34575665, 2021). "Here, these two categories of protein-protein interaction networks depicted that SYK interacted with these genes that are somehow involved in tumor suppression or tumor promotion." (PMID 34575665, 2021). "The SYK gene is broadly communicated in hematopoietic cells, and it is a capable modulator of epithelial cell development and a potential tumor target in human cancers." (PMID 34575665, 2021). "The ACACA, AR, MAPK, PDK1, PEA15, and SYK showed significant differential expression between normal tissues and tumor tissues (P < 0.0001)." (PMID 33842538, 2021). "To better understand the molecular determinants of the SYK kinase pro- and anti-tumor activities, we analyzed existing tyrosine phosphoproteomic datasets that identified SYK targets in different cell types." (PMID 33670716, 2021). "Irish and colleagues first demonstrated that SYK phosphorylation and BCR-mediated signaling occurred more rapidly in FL tumor B-cells compared to non-tumor B-cells, providing a therapeutic rationale for SYK inhibition in this disease." (PMID 33671658, 2021). "Among these upregulated PRC2+-CGI genes, we found many well-defined oncogenes and genes encoding tumor-promoting factors such as MYB, TWIST1, SYK, TEAD4, FOXC1, and FGFR3." (PMID 33931649, 2021). "The promoter methylation level of the SYK gene was higher in COAD than in normal tissues based on sample types, individual cancer stages, patient’s race, gender, age, and weight, tumor histology, and T53 mutation status." (PMID 34575665, 2021). "Tumor-associated genes on Chr9q such as FANCC, NTRK2, SYK, and NOTCH1 were amplified; amplification of BRAF, EZH2, MET, CDK6 and HGF located on Chr7 were also detected." (PMID 34895266, 2021). "SYK has been proposed to possess both a tumour suppressor and tumour promotor activities, depending upon the type of malignancy." (PMID 32292575, 2020). "This interaction has been shown to induce a continuous low-level BCR signal in the tumor cells, resulting in SYK, ERK, and AKT activation, Ca2+ flux, and induction of MYC expression." (PMID 32481736, 2020). "SYK functions as a tumor suppressor in BC with a reduction in SYK expression being associated with poor prognosis and metastasis." (PMID 31178825, 2019).
tumor (continued). "The role of SYK in the tumorigenesis of both hematological and solid malignancies is highly complex, tumor-specific and cell type-dependent, as both tumor promoting and suppressing functions have been described." (PMID 30744170, 2019). "SYK is involved in various biological processes including focal plasma membrane damage-induced necroptosis in red blood cells, while overexpression of SYK in tumor cells leads to senescence." (PMID 29274344, 2018). "To investigate SYK phosphorylation in the tumor cell lines, we used TAK-659, a small-molecule inhibitor of SYK kinase." (PMID 30135222, 2018). "We further assessed the relative abundance of the two SYK isoforms by immunoblotting in matched tumor and normal samples from four additional patients." (PMID 29861861, 2018). "SYK is known to play a role in tumor invasion and progression and migration depending on the cell type." (PMID 29719615, 2018). "SYK mRNA significantly increased in tumor tissues compared with normal counterparts (mean of differences and SEM: 2.08 ± 0.45)." (PMID 29137391, 2017). "Western blot analysis showed that VEGF, MMP9, and phosphorylated SYK protein in tumor tissues of the nude mice decreased with increasing dosage of piceatannol, which was consistent with the in vitro assay." (PMID 29137391, 2017). "When examining consistently altered pathways or kinases across more than one platform, the GNRH, PTEN, STAT3, IL-8, B cell receptor, NF-kB and NO-ROS in macrophages pathways as well as the kinases ERBB2, ERBB3 and SYK were upregulated in tumor tissue." (PMID 28423512, 2017). "The top 10 unpaired normal (n=4 samples) to tumor (n=11 samples) increased protein kinases were SYK, ZAP70, ARG (ABL2), ERBB3, ABL, TEC, MER (MERTK), AXL, EGFR and ERBB2." (PMID 28423512, 2017). "In most epithelial cancers, overall SYK mRNA levels are higher in cancerous cells compared to normal cells of the same organ, including colon, suggesting a tumor promotor role of SYK in tumorigenesis." (PMID 28957395, 2017). "ERBB2, ERBB3 and SYK were functionally more active overall in tumors and TYRO3 was more active in paired tumor samples and also mutated on kinase gene sequencing." (PMID 28423512, 2017). "We applied this method to the study of 70 primary AML bone marrow biopsies and to the development of a critical assay for the reliable measurement of SYK activation in tumor tissue." (PMID 26315286, 2015). "Previously, we have shown that dasatinib (targets mainly SRC family kinases at low concentrations) and PRT318 (highly specific for SYK) exert anti-tumor activity primarily by affecting cell cycle with minimal impact on cell viability." (PMID 26575169, 2015). "To confirm that laminarin anchored to tumor cells activates macrophage cells we measured the phosphorylation of kinase NF-κB p65 (Ser536), a downstream signalling molecule of Dectin-1/SYK signalling pathway." (PMID 24454822, 2014). "SYK has been previously shown to play an important tumor suppressor function during human lymphocyte ontogeny by protecting the lymphoid progenitors from a leukemogenic CK2-mediated inhibition of Ikaros function." (PMID 25506060, 2014). "Differential interactions of SYK with such kinases in a tumor-specific manner are a possible explanation for the dual role of SYK as a tumor suppressor in some cancers, and an oncogene in hematologic malignancies and SCLC." (PMID 24564859, 2013). "Conversely, genes encoding proteins involved in cell growth arrest (i.e. DDIT3, MT3, SYK) are expressed in the invasive rim subpopulations of GBM specimens as compared to their matched tumor core." (PMID 23967279, 2013). "SYK is required for tumor cell survival, and inhibition of SYK with a small-molecule inhibitor caused the degradation of MCL1 and caspase-mediated cell death in RB cells in culture and in vivo." (PMID 23233862, 2012).
tumor (continued). "The tumourigenic mutations of NHERF1 partially or completely disrupt the binding of SYK or merlin, both of which are tumour suppressors, suggesting that NHERF1 converges in a pathway mediated by the two tumour suppressors." (PMID 17078868, 2006). "Hypermethylation of MGMT (in 14 tumours), CDH1 (in nine tumours), RAR-β (in eight tumours) and SYK (in seven tumours) have been found." (PMID 14970867, 2004). "MAPK14 and SYK play important roles in inflammation activation and signal transduction and may inhibit tumor cell proliferation by mediating pyroptosis." (PMID 41008944, 2025). "Combined with the clinical correlation analysis, we hypothesized that neferine may affect the cell cycle of GC through FLT3, CDK6, and SYK to generate an anti-tumor effect." (PMID 40138292, 2025). "Additionally, SIRPα and Siglec-5 recruit SHP-1 and SHP-2 to inhibit SYK phosphorylation, potentially facilitating tumor immune evasion." (PMID 40858654, 2025). "In tumor-associated macrophages (TAMs), Siglec-5 associates with the tyrosine phosphatases SHP-1 and SHP-2 to transmit inhibitory signals, while Siglec-14 interacts with the adapter protein tyrosine kinase SYK to convey activating signals." (PMID 40858654, 2025). "SYK (spleen tyrosine kinase) plays a critical role in regulating cell survival by modulating apoptotic and autophagic pathways, with its effects varying depending on the cellular context and tumor type." (PMID 40507977, 2025). "While TREM-2 has been shown to promote an immunosuppressive environment that might support tumour growth, it also facilitates tissue repair and regeneration through anti-inflammatory pathways such as SYK, NF-kB, PI3K, AKT, and MAPK." (PMID 39684475, 2024). "We also observed a decrease in the number of Treg cells in tumor tissues after inhibiting SYK." (PMID 39261768, 2024). "Therefore, the administration of small molecule inhibitors targeting SYK, including GS-9973, is a potential strategy for treating postoperative liver injury and tumor recurrence in patients undergoing hepatectomy." (PMID 39261768, 2024). "In conclusion, targeting SYK alone or in combination with other immune checkpoint inhibitors is more likely to show a benefit in diffuse glioma with Sub1 by improving the immunosuppressive tumor microenvironment and thus the patient prognosis." (PMID 35910221, 2022). "In pancreatic cancer, Dectin-1 was found to be able to reprogram the tumor-infiltrating macrophages into immune tolerogenic phenotypes and subsequently induce adaptive immunosuppression, which is dependent on the activation of the SYK signaling pathway." (PMID 36131933, 2022). "Considering that SYK might regulate the tumor microenvironment by immunologic biological processes, the role of SYK in the tumor microenvironment needs to be further explored in diffuse glioma." (PMID 35910221, 2022). "However, neutrophils treated with SYK inhibitor showed intact tumor cytotoxicity, excluding this possibility." (PMID 35453656, 2022). "The previous literature showed that the activation of the SYK/NF-κB signaling pathway could accelerate M2 polarization and tumor progression." (PMID 35910221, 2022). "Inhibition of SYK could affect the tumor microenvironment by regulating macrophage polarization and by partially blocking monocyte and B-cell infiltration." (PMID 35910221, 2022). "Furthermore, we explored the expression level of SYK in 21 types of tumor cell lines from the CCLE database, which indicated SYK was universally expressed in all tumor cell lines." (PMID 35910221, 2022). "The abnormal expression of SYK in tumor cells or leukocytes may activate several signaling pathways to promote the release of some chemokines." (PMID 35910221, 2022). "In addition, SYK was significantly over-expressed in 37 pairing tumor tissues, compared with matching peritumoral tissues (p < 0.05)." (PMID 35910221, 2022). "TAK-659 is a dual SYK and FLT-3 inhibitor that targets SYK-expressing tumor cells." (PMID 33980266, 2021).
tumor (continued). "Overall, 5 mutations were observed in the SYK gene from a total of 1393 samples of all tumours, but no hot spot mutations were detected in the active site of SYK." (PMID 32292575, 2020). "To test whether SYK inhibition would also prevent splenomegaly and tumor development, we transferred LMP2A/MYC or MYC primary tumor cells into Rag1KO mice, and once the tumors were palpable, we treated the mice with either TAK-659 or methylcellulose buffer." (PMID 30135222, 2018). "In lymphatic and hematopoietic systems, SYK acts as a tumor promoter." (PMID 29137391, 2017). "SYK plays a dual role as a tumor suppressor and tumor promoter." (PMID 29137391, 2017). "Piceatannol, one pharmacological inhibitor of SYK, attenuated tumor growth in vivo." (PMID 29137391, 2017). "In conclusion, we described that trabectedin affected genes and microRNAs involved in tumor progression and metastatic processes, reflecting data previously obtained at macroscopically level; in particular, we identified SYK and LGALS1 as new putative targets of trabectedin." (PMID 27902465, 2016). "Similarly to human PTCLs, these tumor cells overexpressed SYK, had decreased let-7 expression, increased IL-6 expression, activation of the NF-κB pathway, infiltration by B-cells, and lymphadenopathy." (PMID 27725924, 2016). "The SYK gene can be reactivated by inhibition of DNA promoter methylation in human cancer and may act as a tumor suppressor." (PMID 26096802, 2015). "However, the discovery that SYK is a dual-function kinase with important tumor suppressive and cell cycle regulatory roles represents a new and unexpected challenge for the translational research efforts." (PMID 25506060, 2014). "SYK is a key signalling molecule in immune responses, playing roles in B and T cell activation, Fc receptor signalling, and the regulation of inflammation that may influence the tumour microenvironment and immune checkpoints." (PMID 39457550, 2024). "In addition, SYK was found to contribute to modifying the tumor microenvironment in some tumors." (PMID 35910221, 2022). "Therefore, inhibition of SYK might be a treatment option for modulating the microenvironment and inhibiting tumor progression." (PMID 35910221, 2022). "We also found diffuse gliomas with high-expression SYK consistently exhibited higher immune and stromal scores, compared with those with low-expression SYK in the four cohorts (p < 0.05), which indicated SYK might be involved in regulating the immune and stromal cells in the tumor microenvironment." (PMID 35910221, 2022). "Notably, the deficiency of Dectin-3 or the CARD9/SYK axis in dendritic cells and macrophages resulted in a fungal dysbiosis represented by an increase of C. tropicalis, which subsequently led to an accumulation of MDSC, thus promoting tumor progression." (PMID 36131933, 2022). "Hence, a dual SYK/JAK phenylamino-pyrimidine inhibitor, cerdulatinib (PRT062070), induced apoptosis in cancer cells but not in normal B cells, prevented drug resistance, and caused tumor inhibition in mice." (PMID 33401428, 2021). "SYK is a non-receptor cytoplasmic tyrosine kinase involved in signal transduction in cells of hematopoietic origin, and more recently, implicated both as a tumor suppressor and promoter of cell survival in various hematopoietic and epithelial cancers." (PMID 32977582, 2020). "Also, given the significant transforming role SYK in other tumours, targeting USP10 may have broader applications in cancer." (PMID 32015510, 2020). "Thus, we can speculate that RA may influence tumor progression by targeting the expression of PTK (SYK/SRC), inhibiting the activity of RAS and attenuating the PI3K/Akt pathway and NFκB pathway." (PMID 32867345, 2020). "However, large-scale tumor sequencing studies have not revealed recurrent SYK mutations, and its function in non-hematopoietic cells remains poorly understood." (PMID 25699542, 2015).
tumor (continued). "Additionally, tumor biology unaccounted for in this experience may also impact survival, such as the presence of radioresistant biomarkers like SYK, STAT3, and SKY pathway genes." (PMID 26029663, 2015). "It is worth noting that to date no SYK mutations have been reported in any tumor type." (PMID 24564859, 2013). "A recent separate investigation also showed that during hepatic IRI, crosstalk between neutrophils and macrophage-derived Spleen tyrosine kinase (SYK) drives poor postoperative outcomes and tumor recurrence." (PMID 40867840, 2025). "In prostate cancer, tumor-derived apolipoprotein E (APOE) binds to triggering receptor expressed on myeloid cells 2 (TREM2) on neutrophils, activating DAP12/SYK signaling." (PMID 40805288, 2025). "Our study suggests, for the first time, a connection between SYK and lysosomes in AML, a proposition supported by several studies in non-tumor cells." (PMID 38799454, 2024). "Subsequently, Pharmacological inhibitions of SYK were used to evaluated the effect of SYK on neutrophil recruitment and NETosis, and further explored the effect of SYK on IRI and tumor recurrence." (PMID 39261768, 2024). "Mivavotinib (TAK‐659/CB‐659), a dual SYK/FLT3 inhibitor, reduced immunosuppressive immune cell populations and suppressed tumor growth in combination with anti‐PD‐1 therapy in cancer models." (PMID 38501219, 2024). "When we suppressed the signaling transfer through this cascade by inhibitors of SYK, BTK and PI3 kinases, i.e. by P505-15, ibrutinib and wortmannin, respectively, in Nawalma tumor cells, we observed the relocation of nuclear NFATc1 into cytosol." (PMID 37546418, 2023). "Related drugs, such as Cerdulatinib, is a novel dual SYK/JAK kinase inhibitor and has broad anti-tumor activity in DLBCL." (PMID 37976136, 2023). "BTK, SYK, and HLA-DRB5 were only highly expressed in PH024, and BTK is a small-molecule inhibitor which exhibited impressive anti-tumor activity in clinical studies in patients with various B-cell malignancies." (PMID 35865544, 2022). "Entospletinib (GS-9973) selectively inhibits SYK and presents a synergistic antitumor effect with vincristine, both in a panel of DLBCL cell lines and in a DLBCL tumor xenograft model." (PMID 35205606, 2022). "Even other authors considered GSK3β as a tumor suppressor in CLL, as they showed that GSK3β inactivation by a deregulated SYK/PKCδ pathway stabilized the antiapoptotic Mcl-1 protein." (PMID 36050315, 2022). "There was a statistically significant (p < 0.05) overexpression of SYK in three RB tumors and HFIA in one RB tumor compared to control retina." (PMID 36077715, 2022). "Previously this could only have been identified from tumor tissue in enucleated eyes; however, the work herein demonstrates the ability to detect this from the aqueous humor (alongside methylation signatures of multiple other genes including SYK, MYCN, and others)." (PMID 36130950, 2022). "We found SYK was significantly up-regulated in the 11 types of tumors, including GBM and LGG, and down-regulated in seven types of tumor tissues (KIRC, KIRP, and LUAD) relative to normal tissues (p < 0.05)." (PMID 35910221, 2022). "PIK3R1 and VAV1 are known oncogenes, SYK is a tumor suppressor gene, and PTPN6 has a tumor suppressor role." (PMID 32293263, 2020). "The dual inhibitor cerdulatinib, which targets both spleen tyrosine kinase (SYK, a BCR component) and JAK kinases, potently inhibits tumor growth and induces apoptosis in CLL cells at clinically feasible drug concentrations." (PMID 30542344, 2018). "Our data also show that TAK-659 inhibits SYK phosphorylation and induces apoptosis in LMP2A/MYC tumor cells at low nanomolar concentrations." (PMID 30135222, 2018). "Most interestingly and compatible with the strong SYK inhibition observed in the LMP2A/MYC cells, TAK-659 was able to completely inhibit splenomegaly and tumor development in the Rag1KO mice that had received LMP2A/MYC cells." (PMID 30135222, 2018).